SMAD3 (SMAD family member 3)
Diseases named in the same sentence as SMAD3 in open-access papers (continued):
Sharing a sentence is not in itself a finding about the gene and the disease.
hypospadias (1 paper, 2025). Hypospadias is the displacement of the urethral meatus on the ventrum of the penis. "They indicated that there were low levels of miR-200c expression in hypospadias penile tissues, resulting in the high expression of the Zeb1 gene and protein, thereby activating the TGF-b/Smad3 pathway." (PMID 39624466, 2025).
idiopathic dilated cardiomyopathy (1 paper, 2018). Decreased function of the heart associated with cardiac enlargement and congestive heart failure, of unknown cause. "Here, we report the clinical summaries of three patients harboring a pathogenic SMAD3 variant and displaying idiopathic dilated cardiomyopathy requiring advanced mechanical support in two cases and left ventricular dilatation complicated by malignant arrhythmias in one case." (PMID 29717556, 2018).
Immunodeficiency (1 paper, 2020). Failure of the immune system to protect the body adequately from infection, due to the absence or insufficiency of some component process or substance. "Smad3−/− mice displayed diminished mucosal immunity and impaired T cell response, and died within a few months of severe immunodeficiency and infection." (PMID 32286492, 2020).
Interstitial cardiac fibrosis (1 paper, 2022). A type of myocardial fibrosis characterized by excessive diffuse collagen accumulation concentrated in interstitial spaces. "An experimental animal study found that after blocking Gal-3 function, structural remodeling of the atrial heart, characterized by excessive collagen deposition resulting from interstitial cardiac fibrosis induced by TGF-β/Smad3 signaling pathway, was significantly mitigated." (PMID 36057558, 2022).
intestinal tumor (1 paper, 2007). "Recent studies have indicated that chronic inflammation caused either by infection with Helicobacter pylori or Helicobacter hepaticus is a prerequisite for intestinal tumor development in Smad3-/- and Tgfb1-/-; Rag2-/- mice, respectively." (PMID 17615082, 2007).
invasive breast carcinoma (1 paper, 2023). A carcinoma that infiltrates the breast parenchyma. "Additionally, TGF-β1 present in the tumor-conditioned media (TCM) of invasive breast cancer cells results in SMAD3 activation." (PMID 37682817, 2023).
invasive carcinoma (1 paper, 2013). A carcinoma that is not confined to the epithelium, and has spread to the surrounding stroma. "Minimal tumor formation in DSS-treated Smad3+/− compared to DSS-treated Smad3−/− mice suggests that the presence of at least one copy of SMAD3 is sufficient to protect mice from development of dysplasia and invasive carcinoma." (PMID 24244446, 2013). "Invasive carcinoma was detected in only 1/7 (∼14%, proximal colon mucinous adenocarcinoma) Smad3+/− mice necropsied at the experimental endpoint (27 weeks) compared to Smad3−/− mice, where 10/15 animals (∼67%) developed invasive carcinoma (P = 0.0635)." (PMID 24244446, 2013).
kidney cancer (1 paper, 2014). Primary or metastatic malignant neoplasm involving the kidney. "We used quantitative RT‐PCR to measure the levels of three TGF‐beta pathway components (TGFB2, INHBA, and SMAD3) and two TGF‐beta targets (THBS1 and CDKN2B) which were previously found to be significantly lower in FLCN‐deficient kidney cancer cells and tumors." (PMID 25121506, 2014).
limb-girdle muscular dystrophy (1 paper, 2011). Limb-girdle muscular dystrophy (LGMD) is a heterogeneous group of muscular dystrophies characterized by proximal weakness affecting the pelvic and shoulder girdles. "Sgcg mutations cause limb-girdle muscular dystrophy and Smad3 has been implicated in preventing inappropriate activation of Sgcg gene expression during myogenic differentiation." (PMID 21949838, 2011).
lipodystrophy (1 paper, 2024). A congenital or acquired disorder characterized by abnormal loss or redistribution of the adipose tissue in the body. "TGF‐β‐Smad3‐AKT signaling may provide new therapeutic options for disorders of glucolipid metabolism in the context of lipodystrophy." (PMID 38174807, 2024). "During the development of lipodystrophy, the TGF‐β/Smad3 pathway contributes to the impaired functionality of adipose tissue in nutrient storage." (PMID 38174807, 2024).
liver cirrhosis (1 paper, 2020). "The enhanced expression of Smad2 and Smad3 was observed after the induction of liver cirrhosis." (PMID 32928296, 2020).
macrosomia (1 paper, 2015). "Expression levels of SMAD4, SMAD3, RB1 and EP300 genes were significantly decreased in placentas of neonates with macrosomia compared with those of controls." (PMID 26598317, 2015).
melorheostosis (1 paper, 2021). Melorheostosis is a rare connective tissue disorder characterized by a sclerosing bone dysplasia, usually limited to one side of the body (rarely bilateral), that manifests with pain, stiffness, joint contractures and deformities. "In melorheostosis, SMAD3 mutations may be the main factor in causing increased proliferation of Ob." (PMID 34360745, 2021).
mesothelioma (1 paper, 2022). A usually malignant and aggressive neoplasm of the mesothelium which is often associated with exposure to asbestos. "TGFβ activates SMAD3 to form YAP/TEAD4/SMAD3/p300 complex in regulating the expression of connective tissue growth factor (CTGF) in mesothelioma." (PMID 35602596, 2022).
metastatic colorectal cancer (1 paper, 2019). "SMAD3 is part of the TGF-β signalling pathway and disruption of the SMAD3 gene in mouse results in the onset of metastatic colorectal cancer." (PMID 31147722, 2019). "SMAD3 protein is a transforming growth factor-β (TGF-β) receptor, and disruption of the SMAD3 gene in mouse results in the onset of metastatic colorectal cancer after 4–6 months." (PMID 31147722, 2019).
metastatic melanoma (1 paper, 2015). A melanoma that has spread from its primary site to another anatomic site. "For this, we analyzed phospho-Smad3 and LIF expression levels by immunohistochemistry in a tissue microarray consisting of 24 benign tumors, 56 malignant tumors, and 20 metastatic melanomas." (PMID 25885043, 2015).
metastatic tumors (1 paper, 2024). "Moreover, while no mice from the parental and scrambled KO groups harbored any secondary metastatic tumors, several mice in both the Smad3 and Smad4 groups developed spontaneous liver metastasis." (PMID 38201651, 2024).
Miscarriage (1 paper, 2026). A pregnancy that ends at a stage in which the fetus is incapable of surviving on its own, defined as the spontaneous loss of a fetus before the 22th week of pregnancy. "Multivariate logistic regression analysis by adjusting for all the variables and ROC curve analysis showed that the protein levels of TGFβ2, TGFβR2, Smad3, and p‐Samd3 were all negatively associated with miscarriage." (PMID 41168951, 2026). "Therefore, the (TGFβ2‐TGFβR2)/Smad3/pSmad3 signaling pathway was suppressed in RM versus HC villous tissues and this suppressed pathway was associated with miscarriage." (PMID 41168951, 2026). "In mouse miscarriage model, murine (Tgfβ2‐Tgfβr2)/Smad3/p‐Samd3 signaling in placental tissues are down‐regulated." (PMID 41168951, 2026).
muscular atrophy (1 paper, 2014). The loss of muscle tissue due to inactivity or disease. "Loss of Smad3 was associated with increased levels of Mstn, concomitant with decreased miR-27a/b expression, which is consistent with impaired satellite cell function and muscular atrophy previously reported in Smad3-null mice." (PMID 24498167, 2014).
muscular dystrophies (1 paper, 2024). "SMAD3 overexpression has been associated with muscular dystrophies, according to research." (PMID 39415830, 2024). "SMAD3 overexpression, which is implicated in TGF-beta signaling, may be associated with fibrosis, a prevalent consequence in muscular dystrophies." (PMID 39415830, 2024).
myocardial disease (1 paper, 2024). "The pathogenic role for Smad3 in T2D and T2DN comes from our recent studies that genetic deletion of Smad3 from db/db mice can protect against the development of T2D and T2DN as well as myocardial disease and diabetic dyslipidemia 20-23." (PMID 38164169, 2024).
nephrotic syndrome (1 paper, 2018). A collection of symptoms that include severe edema, proteinuria, and hypoalbuminemia; it is indicative of renal dysfunction. "Among 50 biopsy samples of patients presenting with proteinuria (alone or as a part of nephrotic syndrome), constitutive expression of SMAD3 was detected in all cases in distal tubules and collecting ducts with cytoplasmic and membranous expression pattern." (PMID 30383875, 2018).
neuroblastoma (1 paper, 2022). Neuroblastoma (NB) is the most common solid, extracranial childhood tumor. "Our findings suggest that ATRA-induced differentiation of responsive neuroblastoma cell lines is mediated by the deposition and maintenance of H3K27ac at existing and de novo super-enhancer regions at key transcription factor genes such as HIC1 and SMAD3 to bring about neuronal differentiation." (PMID 36147741, 2022).
neuropathy (1 paper, 2014). A disorder affecting the nervous system that manifests with pain, tingling, numbness, and/or muscle weakness. "Neurological symptoms such as muscle cramps, paresthesia, hypoesthesia and gait disturbance were observed in the majority of SMAD3 gene mutation carriers, half presenting an objective neuropathy." (PMID 24804794, 2014).
oesophageal cancer (1 paper, 2023). "In oesophageal cancer, ATP-binding cassette, sub-family B (MDR/TAP), member 7 (ABCB7) knockdown inhibits TGF-β signalling pathway transduction by promoting SMAD7 expression and repressing SMAD3 expression, inducing apoptosis and suppressing EMT in oesophageal cancer cells." (PMID 37685308, 2023).
Opportunistic infection (1 paper, 2008). An infection that is caused by a pathogen that would generally not be able to cause an infection in a host with a normal immune system. "Targeted disruption of Smad3 in mice results in immune dysregulation and susceptibility to opportunistic infection." (PMID 18616786, 2008).
osteonecrosis of femoral head (1 paper, 2020). "MiR-596 expression was upregulated, while Smad3 expression was inhibited in the bone marrow samples of patients with steroid-induced osteonecrosis of femoral head (SANFH)." (PMID 32410637, 2020).
Overgrowth (1 paper, 2024). Excessive postnatal growth which may comprise increased weight, increased length, and/or increased head circumference. "Cyclosporine-A-induced gingival overgrowth may be alleviated by inducing cell cycle arrest through the downregulation of CDC25A, CDK4/6, CYCLIN D, and pRB, along with the enhancement of SMAD3, SMAD4, and RB in gingival fibroblasts." (PMID 39727652, 2024).
papillary adenocarcinoma (1 paper, 2008). A morphologic variant of adenocarcinoma. "In contrast, Smad4, which oligomerizes with Smad3 to form a trimeric protein complex, was more highly expressed in the papillary adenocarcinomas and may enhance the effect of Smad3 in these tumors." (PMID 18811984, 2008). "Similarly, the higher expression of Smad4 in the papillary adenocarcinoma tumors as potential compensation for the better expression of members the TGF-β-Smad3 pathway in the carcinomas has to be elucidated." (PMID 18811984, 2008).
parasite infection (1 paper, 2024). "Th1-type cellular immunity, Myd88/NF-κB and TGF-β1/Smad3 signaling pathways are activated to exert protective effects against parasite infection in the early stage of E. g infection." (PMID 39436864, 2024).
pediatric asthma (1 paper, 2011). "Our GWAS dataset supported an association between identical SNPs reported in ORMDL3/GSDMB/GSDMA, IL5/RAD50/IL13, HLA-DR/DQ, and SMAD3 and pediatric asthma (P<0.05)." (PMID 21814517, 2011).
Premature ovarian insufficiency (1 paper, 2024). Amenorrhea due to loss of ovarian function before the age of 40.
prolactinomas (1 paper, 2025). "Additionally, molecular markers including DRD2 gene variants, altered expression levels of PRDM2, Filamin A, or PRB3, and dysregulated TGF-β1/Smad3 signaling pathways offer insights into the molecular pathogenesis of aggressive prolactinomas." (PMID 41013821, 2025).
prostate (1 paper, 2019). "This implies that ETV1 overexpression restrains its own oncogenic impact, at least during the initial PIN phase of prostate tumorigenesis, by causing SMAD3/4 overexpression." (PMID 31160676, 2019).
Pulmonary bulla (1 paper, 2025). Pulmonary bullae are rounded focal regions of emphysema with a thin wall which measure more than 1 cm in diameter. "The results showed that the positive rates of p-Smad3 and p-mTOR were higher in Birt–Hogg–Dubé patients compared with simple pulmonary bulla patients, and β-catenin was lower in Birt–Hogg–Dubé patients compared with simple pulmonary bulla patients." (PMID 40677928, 2025).
pulmonary edema (1 paper, 2020). Accumulation of fluid in the lung tissues causing disturbance of the gas exchange that may lead to respiratory failure. "In addition, pretreatment with SIS3 was shown to partially inhibit the phosphorylation of Smad3 and alleviate symptoms including lung injury and pulmonary edema." (PMID 33294466, 2020).
pulpitis (1 paper, 2025). Inflammation of the dental pulp. "Moreover, miR‐223‐3p is associated with pulpitis repair, and its upregulation facilitates odontoblastic differentiation by inhibiting SMAD3, thus promoting increased expression of the dentine‐specific proteins dentine sialophosphoprotein (DSPP) and dentine matrix acidic phosphoprotein 1 (DMP‐1)." (PMID 40497413, 2025).
rectal adenocarcinoma (1 paper, 2019). "TIPE2 overexpression decreased autophagy by reducing the expression levels of p‐Smad2, p‐Smad3, and transforming growth factor‐beta (TGF‐β) in rectal adenocarcinoma cells, however, TIPE2 knockdown showed opposite effects." (PMID 30637920, 2019).
Renal artery stenosis (1 paper, 2017). The presence of stenosis of the renal artery. "Renal artery stenosis (RAS) was established in Wild-type (WT) and Smad3 KO mice (129 genetic background) by placement of a polytetrafluoroethylene cuff on the right renal artery." (PMID 29073282, 2017).
renal dysfunction (1 paper, 2014). "Thus, it is possible that modulation of AKT/GSK3β/SMAD3 by AS101 which leads to attenuation in collagen expression plays a protective role against the development of renal dysfunction." (PMID 25474550, 2014).
renal tumors (1 paper, 2010). "GREM1, TGFB2, INHBA, THBS1 and SMAD3 RNA expression levels were significantly lower in the BHD renal tumors compared to normal kidney tissue." (PMID 20573232, 2010). "Low levels of SMAD3 expression in the BHD tumors may contribute to the ability of these renal tumor cells to escape the growth suppressive effect of TGF-β." (PMID 20573232, 2010). "Notably, several key genes involved in TGF-β signaling, such as TGFB2, INHBA, THBS1 and SMAD3, were down-regulated in FLCN-null and mutant FLCN cells as well as in the BHD-associated renal tumors." (PMID 20573232, 2010). "We measured protein expression of SMAD2, SMAD3, phospho-SMAD3 (pSMAD3) and FLCN in renal tumors from BHD patients (n = 11) and normal human kidney tissue (n = 5)." (PMID 20573232, 2010).
respiratory syncytial virus infection (1 paper, 2017). "H3K4 methyltransferase Smyd3 has been shown to target Foxp3 promoter region to increase its expression, promote iTreg cell development and protect mice from exacerbated inflammation during respiratory syncytial virus infection by a TGF-β-Smad3-dependent mechanism." (PMID 28598443, 2017).
restless legs syndrome (1 paper, 2017). A condition that occurs while resting or lying in bed; it is characterized by an irresistible urgency to move the legs to obtain relief from a strange and uncomfortable sensation in the legs. "The BI-ENRICH algorithm showed that most of the top pathways identified for restless legs syndrome were related to neurodevelopment, including neurogenesis (genes MDGA1, MYT1, NTNG1, and SEMA6D), cell-junction organisation (PKP4 and SMAD3), and axon guidance (NTNG1 and SEMA6D)." (PMID 29029846, 2017).
retinal degeneration (1 paper, 2016). Degeneration of the retina. "After inducing retinal degeneration using 150 mg/l MNU, maximal activation of the TGFβ pathway occurred between days 3 and 8 as demonstrated by immunohistochemistry for phosphorylated Smad3 (P-Smad3) (representative immunohistochemistry for day 5 is shown)." (PMID 27880821, 2016).
Rotavirus infection (1 paper, 2016). Infection with any of the rotaviruses. "A latest research reported that up-regulated miR-142-5p inhibits TGF-β-induced apoptosis via targeting TGFBR2 and SMAD3 in rotavirus infection model." (PMID 27683030, 2016).
serous cystadenocarcinoma (1 paper, 2009). A malignant serous cystic neoplasm usually involving the ovary or the pancreas. "Analysis of Smad3 expression in microarrays of serous cystadenocarcinoma displayed lower levels of Smad3 nuclear expression than benign and borderline tumors and a correlation with N-cadherin expression and poor survival." (PMID 19949545, 2009).
skin changes (1 paper, 2024). "The gene sets encompass numerous genes previously implicated in the pathogenesis of SSc, such as Acta2, Col1a1, Col3a1, Smad3, Ctgf, Msr1, Cd4, Cd8a and Cd68, supporting the potential of anti-PRMT5 in induction of SSc-like skin changes." (PMID 38684324, 2024).
skin squamous cell carcinoma (1 paper, 2012). A carcinoma arising from the squamous cells of the epidermis. "Recently, Hoot and colleagues found that Smad2, but not Smad3, was frequently lost in 83 patients with skin squamous cell carcinoma." (PMID 22539990, 2012).
somatotropinomas (1 paper, 2023). "TGF-β1 and phospho-Smad3 protein were investigated in 13 invasive somatotropinomas and 32 non-invasive somatotropinomas." (PMID 38187082, 2023).
spinal chordoma (1 paper, 2023). A slow-growing malignant bone tumor arising from the remnants of the notochord and occurring in the spine. "In contrast, miR-149-3p triggered apoptosis and suppressed the tumorigenicity of spinal chordoma cells by targeting the Smad3 gene." (PMID 36593242, 2023).
Spontaneous pneumothorax (1 paper, 2019). Pneumothorax occurring without traumatic injury to the chest or lung. "Additional features included spontaneous pneumothorax in SMAD3-related LDS and cervical spine instability in TGFB2-related LDS." (PMID 31569402, 2019).
staphylococcus aureus infection (1 paper, 2021). An infectious process in which the bacteria Staphylococcus aureus is present. "In comparison 2, DEGs in Smad3−/− db/db were significantly clustered in the pathways related to MAPK, complement and coagulation cascades, peroxisome proliferators‐activated receptors (PPAR), staphylococcus aureus infection and steroid hormone biosynthesis." (PMID 33369170, 2021).
stenosis (1 paper, 2022). "This study found that both NF-κB and Smad3 proteins are overexpressed in NEC secondary to intestinal stenosis, and a positive correlation between them was found." (PMID 36474625, 2022). "The expression of Smad3 protein in NEC secondary to intestinal stenosis was higher than that in the control group (66.07% (37 of 56) vs 23.21% (13 of 56), p<0.05)." (PMID 36474625, 2022). "We suspect that the high expression of Smad3 protein in postnecrotizing enterocolitis stricture may promote the occurrence and development of secondary intestinal stenosis." (PMID 36474625, 2022).
suppressor tumors (1 paper, 2021).